CD47 (CD47 molecule)
Diseases named in the same sentence as CD47 in open-access papers (continued):
Sharing a sentence is not in itself a finding about the gene and the disease.
tumor (continued). "The enhanced expression of CD47 in the irradiated tumor microenvironment could severely hamper tumor radiosensitivity." (PMID 32929084, 2020). "Finally, a particularly innovative approach using an oxaliplatin prodrug and a pegylated photosensitizer activated by tumor microenvironment-associated matrix metalloproteinase-2 (MMP2) showed synergy with injection of CD47 antibodies into the tumor." (PMID 35582455, 2020). "CD47 is involved in macrophage-mediated phagocytosis and tumor cell clearance." (PMID 32733941, 2020). "The inhibitory receptor, signal regulatory protein-alpha (SIRPα), negatively regulates macrophage and DC phagocytic activity by interacting with its cognate ligand cluster of differentiation 47 (CD47) overexpressed on many types of cancer cells, increasing tumor invasion and metastasis." (PMID 32456204, 2020). "The potency and the therapeutic effects of anti-CD47 agents varied between different studies according to the type of cancer, type of antibodies, stage of tumor, type of tumor model, drug pharmacokinetics, acquired drug resistanc,e and the state of the immune system." (PMID 32677994, 2020). "Collectively, targeting the immune checkpoint complex CD47-SIRPα has been shown as a promising anti-tumor strategy that may remodel the GBM microenvironment, restore innate and adaptive immunity functions, and improve the prognosis of patients with GBM." (PMID 33329583, 2020). "Furthermore, in vivo, the anti-CD47 treatment is able to shift the macrophage phenotype toward an M1 type and induces anti-tumor effects." (PMID 32322199, 2020). "CD47 expression also differed between CTCs and tumor cells (positive concordance of 11.5%)." (PMID 32041353, 2020). "The CD47/SIRPα axis was defined as an innate immune checkpoint in several tumor models, which stimulates antigen-presenting cell function and consequently the adaptive T cell-mediated anti-tumor immunity." (PMID 32899714, 2020). "Inhibition of CD47 on tumor cells promotes M1 macrophages in the tumor microenvironment, although it is unclear whether this occurs through increased recruitment of M1 macrophages or reprogramming of existing macrophages toward an M1 phenotype 62." (PMID 32685002, 2020). "The results of treating these two kinds of tumor‐derived xenografts with the same method showed that SG635‐SF could block CD47 expression in HO8910 xenografts effectively and recruit relative murine immune cells, including macrophages and NK cells." (PMID 31899582, 2020). "At the same time, hNVs also could bind to macrophages via CD47 and block CD47–SIRPα interaction between tumor cells and macrophages." (PMID 33396603, 2020). "Moreover, we also observed that H2 treatment induced obvious inhibitions in the expression levels of CDC42 and CD47 in mice tumor tissues, as well as reinforced macrophage-mediated phagocytosis in A549 and H1975 cells." (PMID 32314789, 2020). "In xenografts, only tumour cells expressing human CD47 will bind human CD47-targeting reagents, potentially achieving higher concentrations of antibody in the tumour than in syngeneic models where both malignant and normal cells can bind CD47, creating an “antigen sink”." (PMID 31205227, 2020). "Blockade of the CD47 checkpoint may lead to an adaptive anti-tumor response by increasing tumor cell phagocytosis." (PMID 33139625, 2020). "CD47 is widely expressed on all cells but has high expression levels on various tumor cells." (PMID 32802188, 2020). "CD47 has been found expressed on many tumor cells, and it can bind with signal regulatory protein α (SIRPα) on the membrane surface of macrophages, which down-regulates macrophage phagocytosis of tumor cells." (PMID 33251232, 2020). "We also demonstrate enhanced effect of the combinations in vivo as assessed by survival times and tumor sizes in patient-derived orthotopic xenograft (PDX) mouse models of human GBM after treatment with anti-CD47 Ab combined with either irradiation or TMZ chemotherapy." (PMID 31547758, 2020).
tumor (continued). "Interestingly, in this model if mice were treated with CTX before CD47 blockade, they were resistant to tumor re-challenge; however, if CTX was administered after CD47 antibodies, tumor immune memory was impaired and tumor re-challenges grew." (PMID 32704531, 2020). "In addition, it is also possible to activate the adaptive immune response by activating dendritic cells to engulf tumor cells and present tumor antigens to T cells, primarily achieved by inhibiting the CD47-SIRPα axis." (PMID 32733941, 2020). "Second, an anti-CD47 antibody may eliminate tumor cells through Fc-dependent mechanisms, such as antibody-dependent cellular cytotoxicity (ADCC) and complement-dependent cytotoxicity (CDC)." (PMID 33015199, 2020). "Our immunohistochemical results showed that the expression of SF protein in mice could effectively block the CD47–SIRPα pathway, recruit peripheral macrophages and NK cells, and kill tumor cells efficiently." (PMID 31899582, 2020). "Sorafenib could suppress tumor growth via NF-κB signaling pathway, but activated NF-κB mediating CD47 up-regulation promoted sorafenib resistance and its blockade synergized the effect of sorafenib in HCC." (PMID 32670888, 2020). "Overall, miR-128 could serve as an important regulator of tumor immunity through the ZEB1/CD47 axis and EMT in PDAC." (PMID 32536914, 2020). "Finally, CD47 and PD-L1 expression was characterized for the first time in matched tumor and immune cells within the blood and tumor tissue samples and discordance was shown in their distribution between the two compartments." (PMID 32041353, 2020). "Importantly, the antitumor effect was further significantly enhanced when anti-CD47 Ab-coated tumor cell vaccination was given in combination with anti-PD-1 antibody, demonstrating a synergistic effect between the two therapies." (PMID 31996683, 2020). "In addition, low−dose cyclophosphamide reduces CD47 expression on tumor cells, and increases FcγR expression on macrophages." (PMID 32331242, 2020). "Taken together, these findings highlight the significance of the CD47‐SIRPα signaling axis to tumor immune evasion, as this pathway not only limits innate immune clearance of tumor cells but also acts as a barrier to DC‐driven adaptive immunity to cancer as well." (PMID 32508018, 2020). "Even if the signaling cascade of CD47 and its role as a biomarker remain incompletely understood, there is an increasing amount of evidence suggesting that the CD47-SIRPα axis is a potential therapeutic target for the treatment of several neoplasms." (PMID 33015199, 2020). "In addition, exosomes expressing CD47 to protect themselves from phagocytosis by monocytes and macrophages have been used in tumor immunotherapy and have impressive outcomes." (PMID 32746880, 2020). "Similarly, when we treated orthotopically implanted syngeneic GL261 tumors with systemically administered anti-CD47 antibody, we noted a small tumor growth inhibitory effect and survival benefit." (PMID 32198351, 2020). "Rationale: CD47 plays a vital role in the immune escape of tumor cells, but its role in regulating immune-unrelated biological processes such as proliferation and metastasis remains unclear." (PMID 32226539, 2020). "Interestingly, CD47 expression is reported to be reduced by radiation in human papillomavirus-positive cancer resulting in immune-mediated clearance of tumor cells." (PMID 32929084, 2020). "The addition of anti-CD47 antibodies to the tumor enhanced the phagocytosis to 21%." (PMID 33209523, 2020). "(TTI-621) is a checkpoint inhibitor that binds to human CD47 in tumor cells." (PMID 32677994, 2020). "While signals for autophagy may be radioprotective for normal tissue, other studies have shown that blocking tumor autophagy with chloroquine and anti-CD47 is an effective antitumor strategy in vivo." (PMID 35582455, 2020). "Anti-CD47 therapies may inhibit tumor cell proliferation, given that CD47 promotes tumor cell proliferation and metastasis." (PMID 32082311, 2020).
tumor (continued). "Overexpression of CD47 on the tumor cell surface can help these cells escape monitoring and clearance by immune cells, making CD47 a plausible target in the development of novel anti-tumor drugs." (PMID 32082311, 2020). "Thus, the inhibition of CD47 enhances tumor antigen sensing by DCs eliciting effective T‐cell priming and tumor rejection in mice." (PMID 33179413, 2020). "The next step toward identifying SIRPα-CD47 inhibiting SMs was to establish an assay that would enable us to test the ability of lead compounds to inhibit SIRPα binding to CD47 naturally expressed by tumor cells." (PMID 32240171, 2020). "Blockade of CD47 has been proposed as a strategy to overcome innate immune evasion by tumor cells." (PMID 32198351, 2020). "It was demonstrated that MYC positively regulate check point inhibitor proteins leukocyte surface antigen CD47 and PDL1 via direct binding to their encoding gene promoters suppressing both the innate and the adaptive immune response while favoring tumor growth." (PMID 32927768, 2020). "Collectively, these results demonstrated that blockade of CD47 with pep-20 could delay the tumor growth and induce antigen-specific T-cell immune response." (PMID 33020240, 2020). "Thus, blockade of CD47 inhibits phagocytosis, however, PS exposure has been utilized to target tumor cells for macrophage clearance." (PMID 32802188, 2020). ", a CD47 antibody, promoted phagocytosis of tumor cells in ALL cell lines." (PMID 32677994, 2020). "Add anti-CD47 antibody (+ CD47Ab), or IgG antibody (- CD47Ab, control) to each well and incubate for 30 min at 37°C to allow the antibody to block CD47 protein on the surface of the tumor cells." (PMID 33209523, 2020). "Furthermore, anti-CD47 antibody or CD47 blockade treatments have been demonstrated to reduce tumor burden and increase patient survival in various tumor xenograft models." (PMID 32244422, 2020). "Indeed, macrophages were shown to function as APCs and thereby activate the CD8+ T cell population while decreasing priming of CD4+ T cells after anti-CD47-induced phagocytosis of tumor cells." (PMID 32983165, 2020). "The results showed that prodrug vesicle-mediated ICD and CD47 blockade could inhibit tumor growth, suppress metastasis and recurrence of tumor." (PMID 34138136, 2020). "Additionally, CD47-mediated protection against phagocytosis prolongs the retention of exosomes in the extracellular environment, favorable for tumor cells to modulate the tumor microenvironment." (PMID 33505964, 2020). "The potential association of CD47 and HER2 with this cluster of membrane factors may contribute to the pro-tumor growth which may also compromise the radiation-induced anti-tumor immune regulation." (PMID 32929084, 2020). "Only a few studies explored the tumor-intrinsic functions of CD47." (PMID 32226539, 2020). "Moreover, BP-based hyperthermic ablation plus aCD47 treatment induced the polarisation of tumour-specific macrophages towards the M1 phenotype, blocking the ‘don’t eat me’ signal of CD47-SIRPα in tumour cells and thus promoting phagocytosis by macrophages." (PMID 33014356, 2020). "CD47 silence effectively suppressed the tumor growth in a melanoma mice model." (PMID 31903120, 2020). "Of import, our data indicated a tumour suppressive role for AS events in CD47 (ES) and KIF1B (AT)." (PMID 32939931, 2020). "Meanwhile, blocking the interaction between CD47 and TSP-1 with anti-TSP-1 antibodies disrupts tumor-induced osteoclast formation, but deficiency of CD47 alone does not fully recapitulate the effects of antibody-mediated blockade of TSP-1 in either murine or human osteoclasts cells." (PMID 32082311, 2020). "Other studies have identified direct cytotoxicity of CD47-targeting therapies on CD47+ cancer cells, but therapies targeting the SIRPα binding epitope do not cause direct cytotoxicity on tumor cells." (PMID 32082311, 2020). "Inhibiting the CD47–SIRPα interaction generally enhances macrophage-mediated ADCP of tumor cells." (PMID 33256806, 2020).
tumor (continued). "These PTEN-engineered exosomes were simultaneously functionalized with targeting peptide-modified CD47 and were shown to successfully cross the brain blood barrier for targeting restored tumor suppressor function, enhance inhibition of tumor growth, and increase survival." (PMID 33628730, 2020). "Moreover, the simultaneous blocking of CD47 and PD-1 can further prevent the immune escape of circulating tumor cell subsets, thereby inhibiting metastasis." (PMID 32000802, 2020). "Studies have reported that several miRNAs could inhibit tumor growth by regulating the expression of CD47 in cancer cells." (PMID 32536914, 2020). "The blockade of CD47-SIRPα interactions has been shown to enhance the phagocytic activity of phagocytes, such as macrophages, toward tumor cells, thereby resulting in the efficient eradication of tumor cells." (PMID 32149101, 2020). "For example, anti-CD47 treatments have been used to block CD47-SIRPα inhibitory signaling and promote the phagocytosis of tumor cells by macrophages, but anti-CD47 treatments can exert their anti-tumor impact through a number of different mechanisms." (PMID 32082311, 2020). "Indeed, the successful development of Nbs has already been reported against tumor-associated cell-surface markers such as HER2, CD20, PD-L1, CD47, CEA, and PSMA." (PMID 31906437, 2020). "Hence, the documented overexpression of CD47 in GB tumor cells favors the immunosuppressive characteristics of microglia in the tumor microenvironment." (PMID 33585220, 2020). "The cell-surface expression of CD47 was also enhanced in tumors treated with gels containing Dox-iRGD and CpG compared to untreated tumors, presumably as part of the immune evasion mechanism of tumor cells in response to the boosted immune responses." (PMID 33173046, 2020). "In addition, CD47 was highly expressed on the CD133+ tumor-initiating population and was able to trigger their phagocytosis." (PMID 32354198, 2020). "For instance, the absence of CALR might be compensated by the direct injection of recombinant CALR into the tumor or the administration of a CD47-blocking antibody, which neutralizes the main functional antagonist of CALR210,211." (PMID 33243969, 2020). "Several immunosuppressive mechanisms may be involved in the process, such as overrepresentation of immunosuppressive cells (e.g., Tregs) and increased expression of immunosuppressive molecules (e.g., PD-1, CTLA-4, LAG3, and CD47) in the tumor microenvironment." (PMID 32028264, 2020). "These KRASG12D-related engineered exosomes (also termed as iExosomes), together with the modification of CD47 peptides on the surface of iExosomes for escaping phagocytosis, can significantly suppress tumor growth in multiple mouse models of pancreatic cancer and support increased survival." (PMID 33628730, 2020). "For example, genetic engineering has been used tomodify HEK293T cells to generate exosomes that overexpress SIRPα to act as a cancertherapeutic by disrupting CD47-SIRPα interactions between tumor cells and macrophages toattenuate the ability of tumor cells to resist phagocytosis." (PMID 32257533, 2020). "Previous studies have provided evidence that macrophages could effectively phagocytose tumor cells, and dendritic cells (DCs) could elicit increased activation of T cells in the tumor microenvironment after anti-CD47 therapy." (PMID 33020240, 2020). "Moreover, tumor cells can also be eliminated by blocking the CD47–SIRPα pathway through Fc‐dependent mechanisms, which include ADCC and complement‐dependent cytotoxicity effect." (PMID 31899582, 2020). "Then we tested the effect of the tumor microenvironment (TME) on CD47 expression in MM." (PMID 32012878, 2020). "Inhibition of CD47 is a strategy that can facilitate phagocytosis of tumor cells by macrophages." (PMID 32322199, 2020). "Therefore, the activation of TLR signaling pathways in macrophages can synergize with blocking CD47 of tumor cells to enhance PrCR." (PMID 32161718, 2020).
tumor (continued). "In addition, we summarize some tumor therapy strategies at present aimed at macrophages, especially the theoretical basis and the feasibility of blocking the CD47-SIRPα pathway to treat tumors." (PMID 32161718, 2020). "The potential for targeting CD47 as an anti-tumor therapy has reached a new level." (PMID 33224442, 2020). "It is to be noted however that the blockade of CD47–SIRPα interaction with an intact antibody or other tumor opsonizing antibodies also drives antibody-dependent cellular phagocytosis or cytotoxicity by FcRγ-expressing cells such as macrophages, neutrophils or NK cells." (PMID 32273348, 2020). "Improved understanding in this field of research could lead to the development of novel and effective anti-tumor treatments that act through the inhibition of CD47 signaling in cancer cells." (PMID 32082311, 2020). "Disruption of the CD47-SIRPα axis by blockade antibody results in enhanced phagocytosis of different kinds of tumor cells, including increased human and mouse macrophage phagocytosis of tumor cells significantly in vitro." (PMID 33469516, 2020). "Interestingly, anti-CD47 treatment was maximized when started day 1; whereas a slight synergistic tumor inhibition was observed with radiation combined with an anti-CD47 antibody that indeed increased tumor-infiltrated macrophages." (PMID 32929084, 2020). "The lower protection by anti-CD47-coated WT tumor cells than CD47KO tumor cells may possibly be due to quick antibody dissociation from CD47 on tumor cells after intrasplenic injection into mice." (PMID 31996683, 2020). "In our previous study, we identified that CD47 was overexpressed in OSCC lesions and cell lines, and the CD47-SIRP-α interaction inhibited the engulfment of tumor cells by macrophages and promoted M2 macrophages differentiation, mediating the anti-phagocytosis and immune escape of OSCC cells." (PMID 32489584, 2020). "However, regardless of which of these mechanisms prevail in infiltrating NK cells and CD8+ T cells, anti-CD47 immunotherapy in EC will modulate the tumor immune microenvironment." (PMID 32811852, 2020). "While the CD47 signaling cascade remains incompletely understood, recent studies have improved understanding of CD47-dependent signaling and given rise to the development of CD47-targeting anti-cancer therapies that inhibit primary tumor growth and reduce metastasis in various types of cancer." (PMID 32082311, 2020). "SF protein secreted by the infected tumor cells could bind with CD47 receptor on the cell surface and block the binding of anti‐CD47 antibody (ab108415) with it." (PMID 31899582, 2020). "Interestingly, discordant results were also observed regarding the expression of CD47 and PD-L1 on tumor cells between primary and metastatic sites." (PMID 32041353, 2020). "The increased stability of phagocytosed tumor mtDNA within DC following CD47 blockade enables its subsequent release into the cytosol and triggers activation of the cGAS‐STING pathway, which in turn promotes type I IFN production necessary for efficient cross‐priming of antitumor T cells." (PMID 32508018, 2020). "Together, our data clearly showed that tumor-intrinsic CD47 could promote CRC cell proliferation and metastasis in vitro and in vivo." (PMID 32226539, 2020). "We then tested the effect of combining TMZ chemotherapy with anti-CD47 Ab on tumor phagocytosis." (PMID 31547758, 2020). "In preclinical studies, the variation in response to anti-CD47 treatment between cancer type and individual studies could also be a result of differences in the type of tumor model(s) used to test treatment efficacy." (PMID 32082311, 2020). "Chemotherapy may induce the infiltration of TAMs into the tumor, and anti-CD47 therapy could subsequently convert them into effector cells." (PMID 35582455, 2020).